HAGH (hydroxyacylglutathione hydrolase)
Description:
Thiolesterase that catalyzes the hydrolysis of S-D-lactoyl-glutathione to form glutathione and D-lactic acid.
Synonyms: GLO2; HAGH1; GLXII; GLO2D; GLX2
Tractability: Small molecule: it has a binding pocket of medium quality. PROTAC: ubiquitination databases record sites on it; its protein half-life has been measured; a small molecule that binds it is known.
Target class: Enzyme; Hydrolase
Gene: Protein-coding gene on chromosome 16 (1,795,620 to 1,827,157, reverse strand). Ensembl gene ENSG00000063854.
Subcellular location: Mitochondrion matrix (Isoform 1); Cytoplasm (Isoform 2)
Pathways (Reactome):
Metabolism: Pyruvate metabolism
Gene Ontology:
Molecular function: hydroxyacylglutathione hydrolase activity; protein binding
Biological process: glutathione biosynthetic process; glutathione metabolic process; methylglyoxal catabolic process
Cellular component: cytoplasm; mitochondrial matrix; mitochondrion; cytosol
Genetic constraint (gnomAD): Loss-of-function variants: 18 observed, 19.02 expected, observed/expected ratio (o/e) 0.95, 90% interval 0.65 to 1.4. The upper end of that interval is the gene's LOEUF score, 1.4, which puts it in group 5 of 6, group 1 being the genes least tolerant of losing a copy. Missense variants: 364 observed, 337.4 expected, observed/expected ratio (o/e) 1.08, 90% interval 0.99 to 1.18. Synonymous variants: 170 observed, 139.11 expected, observed/expected ratio (o/e) 1.22, 90% interval 1.08 to 1.39.
Homologues: Orthologues: macaque HAGH (97% identical), chimpanzee HAGH (96% identical), mouse Hagh (88% identical), guinea pig HAGH (75% identical), rat Hagh (75% identical), dog HAGH (74% identical), tropical clawed frog hagh (73% identical), zebrafish hagh (71% identical), Drosophila melanogaster tzn (53% identical), Caenorhabditis elegans Y17G7B.3 (39% identical). Paralogues in human: HAGHL (42% identical), PNKD (38% identical), ETHE1 (19% identical), MBLAC2 (15% identical).
Diseases named in the same sentence as HAGH in open-access papers:
HAGH is named in the same sentence as 41 diseases in open-access papers, as found by Europe PMC text mining. Sharing a sentence is not in itself a finding about the gene and the disease. The quoted sentences say what the papers report.
Alzheimer disease (2 papers, 2020 to 2025). A progressive, neurodegenerative disease characterized by loss of function and death of nerve cells in several areas of the brain leading to loss of cognitive function such as memory and language. "It has been reported that plasma levels of HAGH protein are associated with Alzheimer’s disease in carriers of apolipoprotein E." (PMID 40697080, 2025).
autoimmune (2 papers, 2022 to 2025). "Since autoimmune-related genes were significantly repressed by HAGH knockout and autoimmune patients had higher GLO2 levels in leukocytes than healthy individuals, we then assessed the effect of DiFMOC-G on autoimmune disease models." (PMID 39757301, 2025).
colorectal cancer (2 papers, 2020 to 2021). A primary or metastatic malignant neoplasm that affects the colon or rectum. "The down-regulation of HAGH expression has been shown to have significant antiproliferative effects on colorectal cancer." (PMID 33834191, 2021). "The expression of selected genes related to MG degradation III (AKR1B10, AKR1C2 and ADH4), glyoxalase system (GLO1 and HAGH), glucose transport (SLC2A1 and SLC5A1) and colorectal cancer-associated genes (AREG, CXCL8 and CEACAM1) were quantitated using qRT-PCR." (PMID 32561807, 2020).
Hyperglycemia (2 papers, 2023 to 2025). An increased concentration of glucose in the blood. "In addition, HAGH expression levels may reflect brain microvascular endothelial dysfunction related to hyperglycemia." (PMID 36964401, 2023).
cognitive decline (1 paper, 2023). "Since individuals in our study had no overt dementia and since HAGH levels have been found to be increased in NDEs, we can speculate that HAGH could be a prognostic biomarker for cognitive decline, although more studies are warranted to prospectively confirm these results in other cohorts." (PMID 36964401, 2023).
complication (1 paper, 2024). Any disease or disorder that occurs during the course of, or because of, another disease, treatment, or procedure. "In the tibial artery, genetically predicted increased expression of GSTZ1 and PCK2 was causally linked to an increased risk of peripheral circulatory complications in T2DM patients, while HAGH exhibited an opposite causal effect." (PMID 39280009, 2024).
congenital myasthenic syndrome (1 paper, 2021). Congenital myasthenic syndrome (CMS) is a group of genetic disorders of impaired neuromuscular transmission at the motor endplate characterized by fatigable muscle weakness. "For instance, anomalies in PHETA1/2 have been associated with abnormal bone formation resulting in craniofacial defects, HAGH has been associated with skin, bone and joint infections in Yaws disease and mutations in GFPT1 have been associated with muscle weakness in congenital myasthenic syndrome." (PMID 34868271, 2021).
epilepsy (1 paper, 2026). A brain disorder characterized by episodes of abnormally increased neuronal discharge resulting in transient episodes of sensory or motor neurological dysfunction, or psychic dysfunction. "We demonstrated that HAGH, OSBPL1A, and PANK2 constitute core pathogenic mechanisms in epilepsy." (PMID 41810643, 2026).
glioma (1 paper, 2022). A benign or malignant brain and spinal cord tumor that arises from glial cells (astrocytes, oligodendrocytes, ependymal cells).
kidney damage (1 paper, 2023). "In addition, these 106 potential classifiers/biomarkers between TCMR vs. STA are associated with kidney damage (e.g., ATP1B1, CST3, FAH, GSS, HPX and LYZ), tubule injury (e.g., CRYM, GSS, HAGH, HPX and LYZ) and kidney inflammation (e.g., DCN)." (PMID 36814924, 2023).
mild cognitive impairment (1 paper, 2023). "Using the same PEA Olink assay as in the present study, HAGH was found to be increased in plasma from individuals with HIV-associated cognitive impairment, in amyloid β-positive individuals with mild cognitive impairment (MCI) and AD, and in APO E4-carrier individuals with AD." (PMID 36964401, 2023).
Obesity (1 paper, 2023). Accumulation of substantial excess body fat. "This pilot study indicates that the plasma proteins alpha-2-MRAP, HAGH, Siglec-9, MDGA1, EDA2R, and IL12 are negatively associated with cognitive performance in a sample of older adults with overweight/obesity and MetS." (PMID 36964401, 2023). "Here, we showed a significant increase in NPX in 6 proteins (alpha-2-MRAP, HAGH, Siglec-9, MDGA1, EDA2R, and IL12) in the l-GCF group of older adults with overweight/obesity and MetS from the PREDIMED-Plus cohort." (PMID 36964401, 2023).
Stroke (1 paper, 2025). Sudden impairment of blood flow to a part of the brain due to occlusion or rupture of an artery to the brain. "Also, levels of NfL, HAGH, and NMNAT1 were associated when measured at 3 months, but not in the acute stroke phase (p > 0.13 for all, acute phase levels)." (PMID 40316737, 2025).
thyroid (1 paper, 2021). "Finally, we found rs1912998 regulates the expression of IGFALS (P = 1.70E-06) and HAGH (P = 5.08E-07) in thyroid, which is significantly related to thyroid cancer." (PMID 33614667, 2021).
cancer (16 papers, 2012 to 2025). A tumor composed of atypical neoplastic, often pleomorphic cells that invade other tissues. "Low expression of HAGH (GLO2) as well as of LDHD was also prominently connected with poorer 5-year overall survival across different cancers (TCGA PANCAN dataset; N = 11,506 patients)." (PMID 40461450, 2025). "In this pathway, conversion of D-lactate to pyruvate and further to oxaloacetate is increased in cancer cells by upregulation of HAGH, LDHD, and PC." (PMID 36282866, 2022). "Moreover, other metabolic proteins were highly elevated in CRC patients including HAGH and DPEP2 which may reflect the metabolism reprogramming due to CRC tumorigenesis, a well-known hallmark of cancer." (PMID 37228491, 2023). "Higher expression of GAPDH correlates to worse ten-year survival across all cancer types, while the opposite is the case for HAGH (GLO2) and LDHD (PANCAN dataset)." (PMID 40461450, 2025).
neurodegenerative disease (1 paper, 2025). A disorder of the central nervous system characterized by gradual and progressive loss of neural tissue and neurologic function. "Metabolic enzymes NMNAT1 and HAGH (also known as glyoxalase II) clustered together, both involved in cellular processes of importance in neurodegenerative diseases and ageing, including oxidative stress protection." (PMID 40316737, 2025).
HAGH also shares sentences with these, for which no sentence is quoted: tumor (13 papers); breast carcinoma (5); prostate carcinoma (5); diabetes (2); non-small cell lung carcinoma (2); prostate tumor (2); schizophrenia (2); Anxiety (1); autoimmune disease (1); Childhood Cancer (1); chronic granulomatous disease (1); dementia (1); endothelial dysfunction (1); infection (1); insulin-dependent diabetes (1); kidney inflammation (1); lung carcinoma (1); pancreatic carcinoma (1); prostate (1); psychiatric disorder (1); rheumatoid arthritis (1); Salmonella Infections (1); short bowel syndrome (1); skin cancer (1); thyroid cancer (1).